IL10 (interleukin 10)
Diseases named in the same sentence as IL10 in open-access papers (continued):
Sharing a sentence is not in itself a finding about the gene and the disease.
colitis (continued). "Overall, DSS-induced colitis was more severe in IL-10 deficient mice than in WT animals as IL-10 cytokine plays an important role as an anti-inflammatory element with a protective action against colitis." (PMID 22315509, 2012). "IL-10−/−p110δD910A double deficient mice develop a more severe form of colitis, suggesting that the disease caused by p110δ-deficiency is not only a consequence of impaired IL-10 production." (PMID 22912633, 2012). "IL-10-deficient mice die from spontaneous colitis, and this phenotype is partly retained even in mice lacking IL-10 only in Treg cells." (PMID 22969768, 2012). "Colitis was induced in WT and IL-10-deficient mice by oral ingestion of DSS in daily drinking water for 7 days." (PMID 22315509, 2012). "Rederivation of IL-10-deficient mice from conventional SPF environments into germ-free isolators eliminates colitis development, clearly demonstrating the influence of microbiota in the establishment of disease." (PMID 22400037, 2012). "Consistent with this, p110δD910A mice spontaneously develop colitis of similar severity to that observed in IL-10-deficient mice." (PMID 22912633, 2012). "In this study, we find enhanced levels of serum IgG and IgA in IL-10-deficient mice with established and severe colitis, respectively." (PMID 22400037, 2012). "We previously reported the usefulness of FTY720 and KRP-203 in IL-10-deficient mice as a CD-like colitis model." (PMID 21931623, 2011). "It was later found to cause mild to moderate colitis in IL-10-deficient mice and severe IBD only when the mice were coinfected with other, more pathogenic Helicobacter spp." (PMID 21749708, 2011). "FTY720 was also reported to be effective for the treatment of colitis in IL-10-deficient mice, DSS-induced colitis and CD4+CD62L+ cell-transfer model." (PMID 21931623, 2011). "Intragastric administration of this recombinant Lc. lactis strain prevented the onset of colitis in IL-10 KO mice and caused a 50% reduction of the inflammation in DSS-induced chronic colitis." (PMID 21991534, 2011). "We also examined mouse models of colitis, which were induced by trinitrobenzenesulfonic acid, dextran sulfate sodium or interleukin-10 deficiency." (PMID 20074376, 2010). "In a previous study, it was found that rosiglitazone delayed the onset of colitis in IL-10-deficient mice." (PMID 20885923, 2010). "The interleukin-10 gene-deficient (Il10−/−) mouse is a model of human inflammatory bowel disease and Ppara has been identified as one of the key genes involved in regulation of colitis in the bacterially inoculated Il10−/− model." (PMID 20671959, 2010). "IL-10 gene-deficient (Il10-/-) mice develop CD-like colitis mainly in the colon, in part due to inappropriate responses to normal intestinal bacteria including Enterococcus strains, and have therefore been used as an animal model of CD." (PMID 20630110, 2010). "A brief report previously proposed that absence of TLR4 drives aggressive development of spontaneous colitis-associated adenocarcinoma in IL-10−/− mice, but detailed investigations of the underlying mechanisms are so far lacking." (PMID 20803699, 2010). "IL-10-deficient mice developed moderate to severe colitis when exposed to piroxicam (mean histologic scores ± SEM = 30±5)." (PMID 20808919, 2010). "Mast cell deficiency predisposed Il10−/− mice to the development of spontaneous colitis and resulted in increased intestinal permeability in vivo that preceded the development of colon inflammation." (PMID 20808919, 2010). "Apart from its protective effect in clinical studies, VSL#3 was shown to reduce experimental colitis in IL-10-deficient (IL-10−/−) mice." (PMID 19197385, 2009). "In an in vivo model of colitis induced by adoptive transfer of IL–10-deficient cells, administration of N297A significantly reduced body weight loss." (PMID 19172487, 2009). "C. jejuni mono-associated IL-10−/− mice developed rapid and severe colitis, even in the presence of low bacterial inoculum (102 cfu/mouse)." (PMID 19841748, 2009).
colitis (continued). "Il10−/− mice mono-associated with the mildly colitogenic bacterium Bacteroides vulgatus displayed significantly reduced colitis and colorectal tumor multiplicity compared to Il10−/− mice." (PMID 19551144, 2009). "The interleukin 10 (IL10) gene-deficient mouse spontaneously develops colitis after 12 weeks of age." (PMID 18829978, 2009). "The single control mouse (1 of 29) having gross pathology and a high histopathology score tested negative for C. jejuni by both culture and PCR; it was thus a case of spontaneous colitis, which sometimes occurs in IL-10-deficient mice." (PMID 19296832, 2009). "The present study explores the CXCR3 axis and cellular mechanisms that drive Mycobacteria-associated colitis in IL-10-/- mice." (PMID 18533024, 2008). "Here, we present results obtained with the dextran sulfate sodium (DSS) murine models of acute and chronic colitis and chronic colitis in IL-10-deficient (IL-10-/-) mice." (PMID 18331642, 2008). "Contributions of E. coli and other gut bacteria to the aggravation of colitis were shown earlier in mono-associated germ-free IL10-/- and IL2-/- mice and by the curative effects of antimicrobial therapy." (PMID 17653282, 2007). "In contrast, recent findings demonstrated that TLR-signaling via the adapter protein MyD88 is essential for spontaneous development of colitis in IL10-deficient mice." (PMID 17653282, 2007). "This is further supported by in vivo studies where animals genetically deficient in IL-10 develop spontaneous colitis with many of the characteristics of human IBD and clinical studies where IL-10 has shown some benefit in the treatment of human IBD." (PMID 16259632, 2005). "IL-10 appears to play an important role in preventing the onset of IBD, since animals deficient in IL-10 develop colitis spontaneously, and low levels of IL-10 are positively correlated with recurrences of Crohn's disease." (PMID 16259632, 2005). "METHODS: To investigate the contribution of the LALA mutation in the Fc portion to IL-23 neutralization in vivo, we administered anti-IL-23 antibodies bearing either WT or LALA-modified Fc portions to Ig-competent (Il10−/−) and Ig-deficient (Rag2−/−) preclinical colitis mouse models." (PMID 41904387, 2026). "In addition, in a mouse model of colitis, L. johnsonii has been shown to alleviate the associated symptomatology through the activation of anti-inflammatory macrophages and stimulation of IL-10 production via the TLR1/2-STAT3 pathway." (PMID 40869018, 2025). "Interestingly, an increased abundance of Desulfovibrionaceae has been reported to be associated with reduced colitis severity, longer colon length, and elevated IL-10 levels, which are markers of anti-inflammatory and healing responses." (PMID 40282764, 2025). "However, its therapeutic feasibility and mechanisms of action in genetically susceptible colitis models, such as IL-10−/− mice, remain poorly defined." (PMID 41333470, 2025). "Animal studies have demonstrated that infections with Heligmosomoides polygyrus, Schistosoma mansoni and Hymenolepis diminuta can reduce pathological damage associated with colitis, with these protective effects linked to elevated levels of interleukin (IL)-4, IL-10 and TGF-β." (PMID 40597393, 2025). "Furthermore, lamina propria macrophages from IL-10-deficient mice are hyperresponsive to gut microbiota, which results in colitis development." (PMID 40806725, 2025). "Similarly, a simplified human intestinal microbiota (SIHUMI) community has been studied in an interleukin−10-deficient (IL10-/-) mouse model of spontaneous colitis." (PMID 41239968, 2025). "Similarly, H. pylori SS1‐colonized mice exhibit attenuated colitis, associated with elevated IL‐10 and suppressed Th17 responses." (PMID 41473023, 2025). "However, verification of the pathogenicity of type I IFNs requires other experimental colitis models such as trinitrobenzene sulfonic acid-induced colitis and IL-10-deficient mice." (PMID 41155222, 2025).
colitis (continued). "The findings indicated that curcumin effectively mitigated weight loss and colon shortening caused by colitis, enhanced the expression of anti-inflammatory factor IL-10 mRNA (p < 0.05), and suppressed the expression of pro-inflammatory factors (IL-1β, IL-6, and TNF-α mRNA; p < 0.05)." (PMID 40724653, 2025). "Enhanced IL-10 expression of CREB-deficient Tregs prevents T cell-mediated colitis." (PMID 40777015, 2025). "Clostridioides difficile, a Gram-positive anaerobic bacteria causing diarrhea and colitis, and B. fragilis stimulate goblet cells and dendritic cells (DCs) to release interleukin-10 (IL-10) and transforming growth factor-beta (TGF-β), which can increase the regulatory T-cells (T--regss) population." (PMID 41009629, 2025). "Furthermore, transplanting stool from these humanized mice into IL-10-KO colitis-prone mice revealed increased colitis susceptibility in those receiving CD-derived microbiota." (PMID 41277418, 2025). "Some studies report that Nrf2 expression is reduced during active disease, while others demonstrate that pharmacological activation of Nrf2, for example with Bryostatin-1, alleviates colitis in interleukin 10 (IL-10)–deficient mice, an experimental model that mimics Crohn’s disease." (PMID 41462607, 2025). "Deletion of IL‐10 causes spontaneous colitis in mice after 3 months of age." (PMID 40568744, 2025). "Herbal compounds were suggested to inhibit macrophage-mediated inflammatory reaction in a mouse model of ulcerative colitis by downregulating PI3K/Akt/mTOR pathway as well as by diminishing mTORC1-inhibitory effect on autophagy in IL-10-deficient mice that spontaneously develop colitis." (PMID 40806725, 2025). "Moreover, the IL-10-Wnt-β-catenin signaling in intestinal antigen-presenting cells has beenreported to protect mice from colitis-associated colon cancer." (PMID 38706205, 2024). "Interleukin‐10 (IL‐10) is an anti‐inflammatory cytokine that plays an essential role in regulating the immune response and clearing chronic inflammation, and mice with IL‐10 deficiency can develop spontaneous colitis." (PMID 39553425, 2024). "In addition, it has been found that dietary histidine ameliorates colitis by modulating NF-κB activation as well as inhibiting the production of pro-inflammatory cytokines by macrophages in an IL-10-deficient cellular metastasis model of Crohn’s disease." (PMID 39175573, 2024). "The GI disorders studied in the selected studies included dextran sulfate sodium (DSS)-induced colitis, intestinal inflammation caused by reduced IL10, colon perforation, intestinal mucositis, and cadmium-induced intestinal damage, all of which reduced the body weight of the mice." (PMID 39203469, 2024). "Although the exact function of Treg cells is unknown, it is widely believed that Treg cells can reduce the risk of colitis by producing the anti-inflammatory cytokine IL-10." (PMID 38397562, 2024). "Chemicals such as Dextran Sodium Sulfate (DSS), Trinitrobenzene Sulfonic Acid (TNBS), and Dinitrobenzene Sulfonic Acid (DNBS) can be used to induce colitis, as well as spontaneous mutations, adoptive T-cell transfer, microbiome induction, and genetic engineering methods like IL-10 knockout mice." (PMID 38637733, 2024). "Spontaneous colitis has been reported in mice with T cell-specific deletion of the combination of both Prdm1 and Maf, and this pathology was associated with a unique cluster of Treg cells and the abrogation of Il10 expression." (PMID 38609547, 2024). "Indeed, in interleukin-10-deficient (IL10KO) mice which develop spontaneous colitis, food additive-specific alterations in the microbiome and host–microbe interactions accelerated disease onset." (PMID 38892491, 2024). "Although the accurate function of Treg cells is unknown, it is widely believed that Treg cells can reduce the risk of colitis by producing the inflammatory inhibitory effects of IL-10." (PMID 38397562, 2024).
colitis (continued). "The positive association of glycine with IL10 also aligns well with a previous study, wherein glycine exhibited anti-inflammatory effects by reducing colonic expression of IL1β and promoting IL10 cytokines in a colitis mouse model." (PMID 38352704, 2024). "Mutations in IL‐10 and its receptors result in early‐onset colitis in humans." (PMID 35246947, 2023). "Furthermore, various CD1d-expressing cells (e.g., B cells, ILC3s, and macrophages) that can interact with iNKT cells also appear to play protective or pathogenic roles in colitis by producing cytokines (e.g., IL-22 and IL-10) via CD1d-intrinsic signaling." (PMID 38274786, 2023). "Deletion of IL-6 exacerbates colitis and induces systemic inflammation in IL-10-deficient mice." (PMID 38137450, 2023). "However, IL10R-impaired CD4+ T-cells have deficiencies in IL10-secretion and are less capable of suppressing colitis." (PMID 37654482, 2023). "IL‐10 is an important anti‐inflammatory cytokine secreted by regulatory T‐cells (Tregs) and participate in maintaining intestinal homeostasis, its deficiency in mice can cause spontaneous colitis." (PMID 38018589, 2023). "IL-10 is an important immune suppressor, and reduced IL-10R in colorectal tissue might cause severe spontaneous colitis, increasing the risk of CRC initiation." (PMID 38096329, 2023). "An early study conducted on IL-10-deficient colitis-affected mice reported that lactobacillus salivarius and bifdobacterium infantis were able to significantly attenuate colitis, while simultaneously increasing the production of Th1-type cytokines systemically and mucosally." (PMID 36611977, 2023). "Besides its beneficial role, studies however indicate that overexpression of IL-22 results in high antimicrobial peptides production with loss of bacterial diversity in IL10-/- mice, which develop spontaneous colitis compared to IL10-/-IL-22-/- mice." (PMID 37849749, 2023). "However, colitis caused a decrease in IL-10 levels, thus influencing the anti-inflammatory response of this organ." (PMID 37577725, 2023). "Several features of the MMTV infection may combine with IL-10 deficiency to trigger colitis in this model." (PMID 36869359, 2023). "The combination antiretroviral therapy with known activity against MMTV was associated with reduced colonic MMTV RNA and improved histological score in IL-10−/− mice, as well as diminished secretion of pro-inflammatory cytokines and modulation of the microbiome associated with colitis." (PMID 36869359, 2023). "Furthermore, carbon monoxide can inhibit the differentiation of Th17 cells and reduce IL-17 secretion in the mouse colitis model induced by T-cell transfer and in IL-10-deficient mice." (PMID 37554552, 2023). "In addition, mice that are deficient in both MCs and IL-10 exhibit exacerbated colitis compared to single IL-10 knockout mice, which clearly reinforces the relationship between MCs and IL-10." (PMID 37373041, 2023). "Interestingly, the introduction of SFB in SPF-housed 8 weeks old TnfΔARE mice significantly enhanced the abundance of Alistipes species that has been previously reported to trigger colitis and tumor growth in Il-10-deficient mice." (PMID 37004103, 2023). "This probiotic cocktail with an equal mixture of 3 Bifidobacterium and 7 Lactobacillus sub-strains significantly reduced signs and symptoms of DSS-induced colitis and was associated with an increase of IL-10 and decrease of proinflammatory cytokines in the serum." (PMID 36713364, 2022). "We next explored unexamined mechanisms that may underlie the increased severity of colitis in β7-deficient mice, by comparing the cellular composition of the colonic LP between the two strains (β7−/− vs. β7+/+/IL-10−/− mice)." (PMID 34433904, 2022).
colitis (continued). "Our findings allow us to propose an alternate or concurrent explanation for the aggravation of colitis in β7-deficient IL-10−/− mice via intestinal dysbiosis due to a deficient ASC recruitment from PP leading to an intraluminal deficit of IgA and other immunoglobulins." (PMID 34433904, 2022). "Compared with the Enterococcus faecium strain isolated from the faeces of healthy humans, the Enterococcus faecium strain isolated from the faeces of UC patients promoted the pathological score of colitis and the expression of inflammatory factors in colitis-susceptible IL10−/− mice." (PMID 35873168, 2022). "This beneficial effect may be associated with the production of IL-10, as shown in colitis and viral infection." (PMID 36466691, 2022). "Treatment of IL-10-deficient mice with two different antibiotics, both shown to improve scores in patients with Crohn’s disease, attenuated the development of spontaneous colitis." (PMID 36012618, 2022). "In this scenario, as we discovered severe intestinal damage and more severe colitis in the CO diet, this could indicate a dysfunctional compensatory effect of IL-10 in this diet group, given the associated damage in the colon." (PMID 35471119, 2022). "Interestingly, IgA-deficient IL-10−/− mice closely paralleled the phenotype of IL-10−/−/β7−/− mice, inasmuch they developed more severe colitis than IL-10−/− mice." (PMID 34433904, 2022). "The effect of MAdCAM-1 blockade on the microbiota and colitis severity in IL-10−/− cohoused siblings supports a causal effect, induced by the resultant luminal SIgA deficit, expansion of a dysbiotic flora, barrier breach, and possible systemic sepsis as reflected by hypothermia." (PMID 34433904, 2022). "The two models used were DSS-induced colitis and spontaneous colitis in IL-10-deficient mice." (PMID 36613560, 2022). "To explore the intersection between CDI and IBD, we recently described a mouse model where colitis triggered by the murine gut bacterium, Helicobacter hepaticus, in IL-10−/− mice led to susceptibility to C. difficile colonization without antibiotic administration." (PMID 35900107, 2022). "The researchers found that the mouse model of colitis could be established using IL-10 gene knockout mice, demonstrating that IL-10 expression deficiency is associated with the pathogenesis of IBD." (PMID 35795556, 2022). "IL-10 polymorphism is associated with the risk of colitis, implying that genetic variation in the IL-10-dependent pathway may be related to the pathogenesis of inflammatory bowel disease." (PMID 35299671, 2022). "Experimental colitis secondary to adoptive transfer of naïve T cells, 2,4,6-trinitrobenzene sulfonic acid administration, and spontaneous colitis in IL-10 deficiency mouse models are all associated with increased T-bet expression in lamina propria (LP) T cells." (PMID 35660024, 2022). "In addition, IL-10 deficient animals treated with AT-1001, a zonulin peptide inhibitor previously shown to reduce small intestinal permeability, developed less colitis later in life." (PMID 36233559, 2022). "In IL-32γTg mice, the production of IL-10 was associated with less severity of colitis process." (PMID 35097133, 2022). "STING-deficient mice were rescued from IL-10 deficiency-induced spontaneous colitis in mice." (PMID 36467059, 2022). "Furthermore, fecal microbiota transplantation of Blastocystis ST4-altered gut microbiome to colitis mice reduced the severity of colitis, which was associated with increased production of short-chain fat acids (SCFAs) and anti-inflammatory cytokine IL-10." (PMID 35435504, 2022). "Moreover, it has been shown that EEN supplemented with a multifiber mix prompted an expansion of mucosal CD4+ Foxp3+ Tregs along with an increase in concentrations of total SCFAs, i.e., acetate, propionate, and butyrate, in colitis-susceptible mice (IL-10−/−)." (PMID 35323020, 2022).